ODC1 (ornithine decarboxylase 1)
Diseases named in the same sentence as ODC1 in open-access papers (continued):
Sharing a sentence is not in itself a finding about the gene and the disease.
medulloblastoma (2 papers, 2018 to 2022). A malignant, invasive embryonal neoplasm arising from the cerebellum. "Subsequently, the increased level of CNBP protein expression results in the increased translation of ODC1 and associated activation of polyamine metabolism, which is essential for the SHH-dependent proliferation of medulloblastoma cells." (PMID 30360486, 2018). "We observed high copy numbers for the AMPK, CNBP, and ODC1 genes not only in SHH but also in Group #3 medulloblastoma." (PMID 30360486, 2018). "In other words, not only are AMPK, CNBP, and ODC1 genes frequently gained in medulloblastoma, but these gains tend to co-occur more often than expected at random, suggesting that the co-occurrence of these gains may provide a synergistic advantage." (PMID 30360486, 2018). "Interestingly, strong copy number gains are also observed for CNBP and ODC1 in SHH medulloblastoma (19% and 11%, respectively), as well as in Group #3 medulloblastoma (10% and 22%, respectively)." (PMID 30360486, 2018). "Taken together with the complementary report that both SHH and Group #3 medulloblastomas show a high level of expression of CNBP and ODC1 proteins, the SHH/AMPK/CNBP axis could then have a critical role in both the SHH and Group #3 subgroups." (PMID 30360486, 2018).
schizophrenia (2 papers, 2021 to 2023). A major psychotic disorder characterized by abnormalities in the perception or expression of reality.
urothelial carcinoma (2 papers, 2018 to 2020). A malignant neoplasm derived from the transitional epithelium of the urinary tract (urinary bladder, ureter, urethra, or renal pelvis). "In addition, using the same model we will explore the role of other methyl group metabolism genes that we found concomitantly hypermethylated with ODC1 in urothelial carcinoma, like AHCY and AHCYL218." (PMID 32123240, 2020). "Similarly, urothelial carcinoma cells undergo apoptosis after having acquired double-strand DNA breaks following ODC1 interference by siRNA." (PMID 32123240, 2020). "Thus, the dense DNA methylation encompassing the ODC1 5′-regulatory region in most of the analyzed early urothelial carcinoma specimens would be expected to epigenetically impair ODC1 expression." (PMID 29472622, 2018). "Specifically, using two independent techniques, we found increased DNA methylation within the promoter regions of the genes ODC1, ACHY, and MTHFR in early stage urothelial carcinoma tissues." (PMID 29472622, 2018). "Here, using two independent techniques for detecting DNA methylation, we observed DNA hypermethylation of the 5′-regulatory regions of the key methyl group metabolism genes ODC1, AHCY and MTHFR in early urothelial carcinoma." (PMID 29472622, 2018). "Thus, hypermethylation at the 5′-region of ODC1 appears to occur in some, but not all early stage urothelial carcinoma specimens." (PMID 29472622, 2018).
autism (1 paper, 2025). Persistent deficits in social interaction and communication and interaction as well as a markedly restricted repertoire of activity and interest as well as repetitive patterns of behavior. "For example, Bachmann-Bupp syndrome, associated with neurodevelopmental delays and autism, is caused by de novo gain-of-function mutations in ODC1 leading to constitutive activation of ODC and polyamine overexpression." (PMID 40894642, 2025).
basal cell carcinoma (1 paper, 2017). A carcinoma involving the basal cells. "In skin it has been shown that ODC1 gets activated upon UV exposure and is crucially involved in the development of both squamous and basal cell carcinomas." (PMID 28201987, 2017).
diabetic foot ulcer (1 paper, 2025). "Second, while immunohistochemical staining confirmed the expression of CDA and ODC1 in clinical diabetic foot ulcer samples, the limited sample size necessitates larger cohort studies to validate their diagnostic value and clinical significance." (PMID 41322696, 2025).
gastric adenocarcinoma (1 paper, 2026). "Targeting this axis-via ODC1 inhibition or ferroptosis induction-represents a novel therapeutic strategy to reverse treatment resistance in gastric adenocarcinoma." (PMID 41980917, 2026).
gastric tumors (1 paper, 2020). "Furthermore, despite apparent ODC1 downregulation in gastric tumors, its expression positively correlated with cancer pathology—the TNM stage and, particularly, lymph node involvement." (PMID 32630408, 2020). "Moreover, factors indicative of high proliferative capacity—Ki67 and ODC1—were independent predictors of SLC2A1 expression in non-cancerous tissue and gastric tumor, respectively." (PMID 32630408, 2020).
HCMV infection (1 paper, 2020). "Similarly, HCMV infection also stimulates the activity of ODC1 and an increment of the spermine and spermidine levels." (PMID 32373551, 2020).
hepatoblastoma (1 paper, 2020). Hepatoblastoma (HB) is a malignant hepatic tumor and is the most common pediatric liver cancer. "In summary, the current results propose a DNA methylation-based classification that explains the genetic and clinical diversity of hepatoblastoma and shed light on the high expression of NQO1 and ODC1, potential druggable targets, in high-risk hepatoblastoma." (PMID 32656360, 2020). "Another valuable finding of the current study is the identification of novel therapeutic targets, NQO1 and ODC1, in high-risk hepatoblastoma." (PMID 32656360, 2020). "Moreover, ODC1 was among the most differentially upregulated genes in high-risk hepatoblastoma cases." (PMID 32656360, 2020). "Altogether, we hypothesized that ODC1 was a key molecule for aggressive cell proliferation and a candidate therapeutic target in high-risk hepatoblastoma." (PMID 32656360, 2020). "Our cell proliferation assay to investigate whether ODC1 inhibition suppressed cell growth in ODC1-high hepatoblastoma cell lines revealed that both ODC1 siRNA and difluoromethylornithine (DFMO), an ODC1 inhibitor, significantly inhibited cell proliferation." (PMID 32656360, 2020).
HIV-1 infection (1 paper, 2023). The type species of lentivirus and the etiologic agent of acquired immunodeficiency syndrome (AIDS). "While HIV-1 infection boosted the frequency of TregDys, blockade of ODC-1 activity significantly diminished TregDys to the levels in uninfected cultures (bottom)." (PMID 36693889, 2023). "Given the dominant role of ODC-1-polyamine-EIF5A hypusination axis in promoting TregDys induction and proliferation during HIV-1 infection, we anticipated elevated levels of ODC-1 expression in TregDys." (PMID 36693889, 2023). "To examine polyamine metabolism, we first focused on ODC-1 expression during HIV-1 infection in vitro." (PMID 36693889, 2023). "ODC-1 blocking and GC7 inhibited the FOXP3 induction during HIV-1 infection." (PMID 36693889, 2023). "Importantly, ODC-1 inhibition significantly diminished HIV-induced intracellular increases in putrescine, spermidine, and spermine, showing the critical function of ODC-1 in enhancing polyamine levels during HIV-1 infection." (PMID 36693889, 2023).
hyperlipidemia (1 paper, 2025). "Therefore, the increase of ODC1, and consequently polyamine metabolites, caused by hyperlipidemia in MS, is an important mechanism in the progression of EC." (PMID 41402312, 2025). "Oleic acid, one of the many components in hyperlipidemia, is the key factor for upregulating Ornithine Decarboxylase 1 (ODC1) (the rate-limiting enzyme in polyamine metabolism) and downstream polyamines." (PMID 41402312, 2025).
intestinal tumour (1 paper, 2023). "Although in established Apc-null intestinal tumours mTORC1 and ODC1 activity promote tumour progression, the role of these pathways in early intestinal tumour formation in response to refeeding is unclear." (PMID 36711807, 2023).
latent infection (1 paper, 2022). "We observed multiple genes in polyamine pathway, including ODC1, SRM, SMS and DHPS, were significantly dysregulated due to KSHV latent infection." (PMID 35486659, 2022). "ODC1, the rate-limiting enzyme of the polyamine synthesis pathway, was found upregulated due to KSHV latent infection, consistently with the previous finding that ODC1 gene expression is subjected to transcriptional regulation by c-Myc that is upregulated by LANA." (PMID 35486659, 2022).
leukoplakia (1 paper, 2025). A white patch or plaque on a mucous membrane that cannot be characterized clinically or pathologically as any other disease. "Although our analysis compared OSCC to BC samples, 19 significant genes overlapped with Farah and Fox’s 47 differentially expressed genes (DEGs), including the upregulation of ODC1 and LCN2 and the downregulation of COL1A1, COL11A1, and STAC2 in dysplastic leukoplakia samples." (PMID 40650045, 2025).
liver fibrosis (1 paper, 2022). "Moreover, CYP1A1, ODC1 and MAOB may be potential targets related to the anti-liver fibrosis effects of dehydrocarptin, tetrahydropalmatine and palmatine, respectively." (PMID 36676934, 2022). "Furthermore, CYP1A1, ODC1 and MAOB comprise the intersection of TACS targets, metabolic pathway targets and disease-related targets, and dehydrocavidine, tetrahydropalmatine and palmatine are considered as potential active compounds for CCl4-induced liver fibrosis therapy." (PMID 36676934, 2022).
lung adenocarcinoma (1 paper, 2024). A carcinoma that arises from the lung and is characterized by the presence of malignant glandular epithelial cells. "In addition, we validated the upregulated ODC1 expression and polyamine synthesis in lung adenocarcinoma tissue compared with adjacent normal tissue." (PMID 38504107, 2024).
Macrocephaly (1 paper, 2021). Occipitofrontal (head) circumference greater than 97th centile compared to appropriate, age matched, sex-matched normal standards. "This evidence points to a critical window and location of ODC1 expression within the developing brain that correlates to gain-of-function variants resulting in macrocephaly (over proliferation of neurons) or loss-of-function variants to microcephaly (under proliferation of neurons)." (PMID 33806076, 2021).
mastitis (1 paper, 2022). Inflammation of breast tissue during lactation or postpartum due to an obstructed duct or infection. "Of the 12 co-expressed down-regulated genes, TFRC and MAPK6 are thought to be associated with immunity and mastitis, LARP1B and ODC1 are associated with reproductive traits, such as oestrogen and sperm quality." (PMID 35480317, 2022).
memory impairment (1 paper, 2025). "The presence of Aβ changes the urea cycle from linear to cyclical: the reduction of ODC1 promotes the conversion of ornithine to dextran, eliminating dextran, ammonia, and H2O2 to reduce GABA and alleviate memory impairment." (PMID 40859959, 2025).
Neurodevelopmental delay (1 paper, 2021). "At least four aspects make genes such as ODC1 difficult to establish neurodevelopmental delay association with our classical sequencing and statistical analysis." (PMID 33806076, 2021). "The linkage from the expression data of ODC1 in early neural progenitor proliferation to phenotypes of neurodevelopmental delay and to the connection of polyamine metabolites in brain function establish ODC1 as a bona fide neurodevelopmental disorder gene." (PMID 33806076, 2021). "The linkage from the expression data of ODC1 in early neural progenitor proliferation, to phenotypes of neurodevelopmental delay and brain area PheWAS, to the connection of polyamine metabolites in brain function establish ODC1 as a bona fide neurodevelopmental disorder gene." (PMID 33806076, 2021).
Obesity (1 paper, 2025). Accumulation of substantial excess body fat. "No statistically significant survival difference was observed between patients with obesity and normal-weight patients with high ODC1 expression." (PMID 41402312, 2025).
odontogenic tumors (1 paper, 2022). "Among others, ornithine decarboxylase 1 (ODC1), a gene involved in cell cycle regulation and proposed as a marker of dental epithelium (moreover aberrantly expressed in specific odontogenic tumors), is higher expressed in P4 versus P4-switch organoids." (PMID 35217915, 2022).
osteosarcoma (1 paper, 2025). A usually aggressive malignant bone-forming mesenchymal neoplasm, predominantly affecting adolescents and young adults. "Given AZIN1’s known role in regulating ODC1 stability and activity, we hypothesized that AZIN1 overexpression underlies the dysregulated arginine-polyamine metabolism characteristic of osteosarcoma." (PMID 40246846, 2025). "Given the established function of polyamines in cell cycle regulation, we hypothesized that AZIN1 promotes the osteosarcoma cell cycle by modulating ODC1 activity and, consequently, polyamine synthesis." (PMID 40246846, 2025).
skin aging (1 paper, 2023). The gradual irreversible changes in structure of skin that occur as a result of the passage of time.. "Then, we confirmed the down-regulated expressions of ABCC4, PTGER3, BCEH, HPGD, and MOXD1 in normal group, while AR, CXCR2, HSD17B2, ODC1, PI3, PLAU and THBS2 were up-regulated in skin aging group." (PMID 37310405, 2023).
Snyder-Robinson Syndrome (1 paper, 2018). "The common neurological phenotypes resulting from mutations in SMS, ODC1, and TSC and their association with dysregulated polyamine metabolism suggest that the knowledge obtained from the current studies might serve to benefit a patient population beyond those with Snyder-Robinson Syndrome." (PMID 30544565, 2018).
triple-negative breast carcinoma (1 paper, 2021). An invasive breast carcinoma which is negative for expression of estrogen receptor (ER), progesterone receptor (PR), and human epidermal growth factor receptor 2 (HER2). "Treatment with a dual inhibitor of A1R and ornithine decarboxylase 1, ODC-MPI-2, increased cAMP levels and reduced polyamine production, ultimately leading to growth inhibition in triple-negative breast cancer (TNBC) cell lines." (PMID 34830449, 2021).
ulcerative colitis (1 paper, 2024). An inflammatory bowel disease involving the mucosal surface of the large intestine and rectum. "AHR expression was positively correlated with ODC1 in intestinal mucosal biopsies from patients with ulcerative colitis." (PMID 39113799, 2024).
tumor (121 papers, 1997 to 2026). "ODC1, a rate-limiting enzyme in the polyamine metabolic pathway, has been widely reported to be closely associated with tumor progression and poor prognosis across multiple malignancies." (PMID 41573681, 2025). "In various NB initiation and progression models, elevated levels of LIN28B, MYCN and ODC1 have been associated with increased tumor initiation and progression due to increased proto‐oncogene activity and ensuing progenitor‐like cells." (PMID 38686627, 2024). "Further analysis of the transcriptome and chromatin landscape of PDA cells following OAT or ODC1 knockdown revealed significant changes in gene expression and chromatin accessibility associated with suppressed tumor-growth." (PMID 37884518, 2023). "Other genes that are associated with poor prognosis and tumor progression, such as ODC1, ERN1, and ETS2, were also downregulated primarily in the samples treated with Se-E2, Se-K2 and Se-C3." (PMID 36839934, 2023). "ODC1 has been implicated as an important gene during the early stages of tumor progression and is highly expressed in a variety of cancer types." (PMID 33918978, 2021). "Functionally, ODC1 depletion inhibited proliferation, migration, invasion, and tumor growth in vitro and in vivo, while its overexpression exacerbated malignant phenotypes." (PMID 41980917, 2026). "Ornithine decarboxylase 1 (ODC1), as a key rate-limiting enzyme in the polyamine synthesis pathway, is highly activated in tumor cells and plays a significant role in tumor initiation and progression." (PMID 40137165, 2025). "In the context of GC, both ODC1 and ALDH18A1 were abnormally expressed in tumor cell lines, and their expression was associated with multiple signaling pathways linked to disease progression." (PMID 41573681, 2025). "Oleic acid-HOXB9-ODC1 stable cascading axis then is confirmed in patient tissues, and ODC1 inhibitors boost patient-derived tumor cells’ chemosensitivity." (PMID 41402312, 2025). "This long-term positive feedback in a continuous daily cycle has a more profound impact on HOXB9, ODC1, polyamine accumulation, and tumor progression than mere upregulation." (PMID 41402312, 2025). "We validated key enzymes in the polyamine pathway and found an increase in ODC1 in tumor tissues of patients with MS." (PMID 41402312, 2025). "Ishikawa cells stably transfected with sgRNAs targeting HOXB9 exon 1 and ODC1 exon 4 were used to establish a subcutaneous xenograft tumor model." (PMID 41402312, 2025). "Difluoromethylornithine is a highly effective and specific inhibitor of ODC1 and its treatment resulted in intracellular polyamine depletion, cell cycle arrest, thereby inhibiting tumor cell growth." (PMID 38395945, 2024). "Immunohistochemistry was utilized to assess the expression of SMOX and ODC1 in tumor tissues of mice in each group." (PMID 39439459, 2024). "One intermediate product of the UC is ornithine decarboxylase 1 (ODC1), a specific substrate that is essential for the production of polyamines during tumor growth." (PMID 39096436, 2024). "This suggests that L.p CMU-Pb-L5 reduces c-Myc expression, inhibiting ODC1 transcriptional activity, and thus polyamine biosynthesis, ultimately inhibiting tumor growth." (PMID 39439459, 2024). "This indicates that L.p CMU-Pb-L5 inhibits polyamine synthesis by suppressing SMOX and ODC1 expression, thereby reducing polyamine levels in tumor tissues and inhibiting tumor growth." (PMID 39439459, 2024). "Conversely, the M2 type metabolizes arginine by arginase 1 (Arg1) and then by ornithine decarboxylase 1 to produce PAs for pro-tumor activities." (PMID 39191486, 2024). "The results demonstrated varying degrees of expression of SMOX and ODC1 in the tumor tissues of all groups." (PMID 39439459, 2024). "SLC3A2 has been shown to be one of the proteins involved in the polyamine transport pathway in NB, and in combination with DFMO (ODC1 inhibitor), was shown to inhibit tumor development in TH-MYCN transgenic mice." (PMID 38858548, 2024).